NOX4 (NADPH oxidase 4)
Diseases named in the same sentence as NOX4 in open-access papers (continued):
Sharing a sentence is not in itself a finding about the gene and the disease.
cardiac hypertrophy (65 papers, 2010 to 2025). "NOX4 is particularly implicated in angiotensin II-induced cardiac hypertrophy and fibrosis, while NOX2 can contribute to oxidative stress and myocardial dysfunction." (PMID 39456418, 2024). "Experiments with diabetic rats have shown that NOX2 and NOX4 proteins are also associated with cardiac hypertrophy and fibrosis, while mice subjected to high fat diets demonstrated elevated NOX2 proteins associated with increased cardiomyocyte size." (PMID 36012897, 2022). "NOX2 and NOX4 have also been found to be associated with cardiac hypertrophy and fibrosis in diabetic rats, and the elevation of NOX2 has been shown to be associated with an increase in cardiomyocytes size in mice subjected to high fat diet." (PMID 34660744, 2021). "We also found that a constitutive increase in endothelial Nox4 is associated with modest eccentric cardiac hypertrophy with physiological characteristics, that is, preserved systolic and diastolic contractile function." (PMID 33511759, 2021). "This study further demonstrated that treatment with angiotensin II caused cardiac hypertrophy and myocardial fibrosis along with NOX4 upregulation and ROS production in control mice, and all these changes were much more aggravated in hNOX4." (PMID 33953837, 2021). "While NOX2 causes cardiac hypertrophy through angiotensin II, NOX4, which partially localizes to the mitochondria, is associated with cardiac hypertrophy due to increased pressure overload from myocardial stresses in the failing human heart." (PMID 31857574, 2019). "One of these subunits, NOX4, was implicated in Ang II infusion and/or pressure overload-induced myocardial hypertrophy." (PMID 22848833, 2012). "Similarly, when these NOX4-deficient mice were exposed to continuous phenylephrine infusion, they exhibited less cardiac hypertrophy and oxidative stress." (PMID 41009041, 2025). "Setanaxib (GKT137831), a dual NOX1/NOX4 inhibitor, attenuated cardiac hypertrophy, fibrosis, inflammation and oxidative stress in TAC-, doxorubicin-, and isoproterenol- induced heart failure models." (PMID 41009041, 2025). "This targeted delivery system shows promise as an efficient strategy for treating cardiac hypertrophy, underscoring the potential of localized, precise NOX4 inhibition as a therapeutic avenue." (PMID 41009041, 2025). "A more targeted approach to NOX4 inhibition has shown promise in preclinical models of cardiac hypertrophy: a strategy using cell-derived vesicles (CEVs) loaded with small interfering RNA targeting NOX4 (siNOX4) was developed." (PMID 41009041, 2025). "Transgenic cardiac-specific deletion of NOX4 in FYN-knockout mice subjected to TAC rescued the exaggerated cardiac hypertrophy, reduced cardiac ROS production and apoptosis." (PMID 41009041, 2025). "Specifically, NOX4 overexpression exacerbated left ventricular (LV) contractile dysfunction and cardiac hypertrophy following TAC, and induced adverse cardiac remodeling to phenylephrine." (PMID 41009041, 2025). "Cardiac-specific overexpression of NOX4 increased survival rate by preserving LV systolic and diastolic function, and decreased cardiac hypertrophy, fibrosis and metalloproteinase activity, in transgenic mice subjected to left coronary artery ligation." (PMID 41009041, 2025). "In vivo, delivery of anti-NOX4-siRNA encapsulated in heart-targeting small extracellular vesicles improved LV contractile function and reduced cardiac hypertrophy in C57BL/6 mice chronically infused with angiotensin II." (PMID 41009041, 2025). "On the one hand, increased NOX4 expression and activity were reported in heart failure patients and in experimental models of cardiac hypertrophy." (PMID 38426206, 2024). "In the heart, NOX4 is involved in angiotensin II-induced cardiac hypertrophy and fibrosis, and its activity contributes to the activation of fibrotic signaling pathways such as transforming growth factor-beta (TGF-β)." (PMID 39456418, 2024).
cardiac hypertrophy (continued). "Collectively, these data suggest that the interaction between FYN and NOX4 is essential for regulating FGF18 against myocardial hypertrophy." (PMID 36871047, 2023). "Taken together, these results suggested that FGF18 upregulates FYN activity, which in turn negatively regulates NOX4 activity and then prevents cardiac hypertrophy." (PMID 36871047, 2023). "NOX4 regulates metabolic reprogramming in various diseases, such as cardiac hypertrophy, cancers, and pneumonia." (PMID 37044213, 2023). "Previous studies have demonstrated that GLP-1R agonist inhibits NOX4-mediated ROS production in high-glucose cultured endothelial cells or angiotensin II-induced cardiac hypertrophy." (PMID 37278349, 2023). "Of these proteins, NOX4 is known to make the most significant contribution to myocardial hypertrophy and is regarded as a cardiac reflection of oxidative stress." (PMID 35476142, 2022). "In vivo experiments about cardiac hypertrophy have displayed inhibiting effects for Nobiletin on NOX4 and NOX2 expression, which can suppress ER stress." (PMID 36703744, 2022). "In this model of transient overexpression of NOX4 in the heart, NOX4-induced exacerbated Ang II-cardiac hypertrophy via increased ROS production has been reported." (PMID 36359731, 2022). "In cardiomyocytes and cardiac fibroblasts, Ang II activated Rac1 (increasing expression of RAC1-GTP), as well as NOX2 and NOX4 involvement in cardiac hypertrophy and fibrosis has been indicated." (PMID 36359731, 2022). "Another study came to the significant conclusion that XBP1s promotes cardiac hypertrophy triggered by NADPH oxidase 4 (NOX4) by activating RIPK1-related NF-κB signaling." (PMID 36547457, 2022). "Besides, NOX4 was found to be upregulated in our analysis and confirmed the results by Matsushima S that NOX4 expression in cardiomyocytes was increased in response to phenylephrine stimulation, and that cardiac-specific Nox4 knockout could relieve myocardial hypertrophy caused by pressure overload." (PMID 35964009, 2022). "NOX2 and NOX4, for example, regulate distinct redox signaling mechanisms in cardiac myocytes pertinent to the onset and progression of cardiac hypertrophy and heart failure." (PMID 36139898, 2022). "A chronic increase in endothelial Nox4 stimulates physiological cardiac hypertrophy and protects against AngII‐induced cardiac fibrosis by inhibiting EC activation and the recruitment of inflammatory cells." (PMID 33511759, 2021). "It was reported that a high level of cardiomyocyte‐specific Nox4 overexpression, with eight‐fold greater ROS production, exaggerated AngII‐induced cardiac hypertrophy and fibrosis." (PMID 33511759, 2021). "Endogenous Nox4 is required for the full development of eccentric cardiac hypertrophy and remodelling during chronic volume overload." (PMID 31821410, 2021). "Despite this difference regarding oxidative products, it has been reported that Nox4 and Nox2 upregulation is related to cardiac hypertrophy." (PMID 33202984, 2020). "A study established an increase in Nox2 and Nox4 expression in cardiac hypertrophy under chronic normobaric hypoxia." (PMID 33202984, 2020). "In another model of cardiac-specific deletion of Nox4, cardiac hypertrophy, fibrosis, and apoptosis after pressure overload was reduced, suggesting different cell and dose-dependent responses of Nox4 in CVD." (PMID 32630452, 2020). "Our previous study indicated that NADPH oxidase 4 (Nox4) promotes angiotensin II (Ang II)‐induced cardiac hypertrophy through the pathway between reactive oxygen species (ROS) and a disintegrin and metalloproteinase‐17 (ADAM17) in primary cardiomyocytes." (PMID 30953402, 2019). "Phenylephrine induces cardiac hypertrophy in mice via oxidation of histone deacetylase mediated by Nox4-dependent ROS." (PMID 31827673, 2019).
cardiac hypertrophy (continued). "It is important to note that a later study from the Sadoshima laboratory found that global Nox4 KO mice had exaggerated cardiac hypertrophy, dysfunction, and fibrosis as compared to WT controls after TAC22 (shown in online figure XVI in that paper)." (PMID 29040462, 2018). "Under this type of stress, a Nox4 knockout model was observed to be more sensitive than wild-type animals, showing an exacerbated cardiac hypertrophy and fibrosis." (PMID 28505091, 2017). "It has also been reported that Nox4 directly mediates mitochondrial dysfunction, oxidative stress, and myocardial cell death during pressure overload-induced cardiac hypertrophy." (PMID 28479925, 2017). "Nox4 activation has been reported contributes to cardiac hypertrophy, myocardial infarction, and heart failure." (PMID 28230797, 2017). "The group led by Shah demonstrated that, while Nox2 mediates cardiac hypertrophy upon pressure overload, Nox4 showed a protective effect." (PMID 28505091, 2017). "We previously showed that aging upregulates Nox4 and that upregulation of Nox4 in the nucleus promotes cardiac hypertrophy through oxidation and nuclear export of histone deacetylase 4 (HDAC4)." (PMID 25132912, 2014). "In contrast, NOX4, which is constitutively active at a low level, can be induced by pressure overload and mediates cardiac hypertrophy mainly by apoptosis." (PMID 23861715, 2013). "That is to say, NOX2 plays an important role in mediating angiotensin-II-induced cardiac hypertrophy through MMPs, while NOX4 mediates cardiac hypertrophy and heart failure in response to pressure overload mainly by apoptosis." (PMID 23861715, 2013). "Using cardiac-specific Nox4 KO mice, we have shown recently that Nox4 is an important source of oxidative stress in mitochondria during cardiac hypertrophy and failure." (PMID 21212466, 2010). "Notably, endothelial-specific NOX4 overexpression led to physiological cardiac hypertrophy with preserved function, suggesting broader roles for NOX4 in cardiovascular remodeling." (PMID 41009041, 2025). "In contrast, other studies reported that cardiac-specific NOX4 overexpression preserved cardiac function and reduced hypertrophy after 9 weeks of TAC, whereas systemic or cardiac-specific NOX4 deletion in that context worsened cardiac remodeling, pointing instead to a protective role for NOX4." (PMID 41009041, 2025). "In transgenic mice subjected to TAC surgery (suprarenal banding) for 9 weeks, cardiac-specific overexpression of NOX4 was reported to preserve cardiac function and decrease cardiac hypertrophy and fibrosis, by increasing angiogenic markers expression and fatty acid oxidation." (PMID 41009041, 2025). "Previous studies have shown that Nox4 promotes cardiac hypertrophy via the ROS/ADAM17 pathway." (PMID 37528096, 2023). "This study uncovered the previously unknown cardioprotective effect of FGF18 mediated by the maintenance of redox homeostasis through the FYN/NOX4 signaling axis in male mice, suggesting a promising therapeutic target for the treatment of cardiac hypertrophy." (PMID 36871047, 2023). "We first investigated whether BRD4-mediated Nox4 inhibition contributes to BEL efficacy in ISO-induced cardiac hypertrophy." (PMID 37528096, 2023). "In vascular smooth muscle cells and cardiomyocytes ontogenically related to VSMCs, high NOX4 expression induced by ER stress reduced cell death but promoted cell proliferation, leading to arterial remodeling and myocardial hypertrophy, and exacerbated the deterioration of cardiac function." (PMID 36704356, 2022).
cardiac hypertrophy (continued). "CD20 downregulation has been associated with reduction of NOX4 and ROS levels and further cardiac hypertrophy inhibition, whereas ectopic CDC20 expression enhanced cardiac hypertrophy via direct degradation of the autophagy regulator LC3 and further autophagy impairment." (PMID 36012897, 2022). "Thus, the positioning and activity of NOX2 at sarcolemmal membrane domains and NOX4 at intracellular membranes dictate the topography of redox signaling that can have instrumental roles in cardiac hypertrophy and diastolic dysfunction." (PMID 36139898, 2022). "Additionally, cardiac-specific overexpression of NOX4 in mice potentiated Ang II-induced cardiac hypertrophy, which is inhibited by GKT137831 administration." (PMID 36359731, 2022). "Moreover, NOX4 overexpression further promoted cardiac hypertrophy, fibrosis, and oxidative stress in response to AngII." (PMID 36139898, 2022). "In the TAC model, the absence of NOX4 attenuate the production of O2•- and alleviates cardiac hypertrophy and cardiac remodelling caused by pressure overload." (PMID 36204518, 2022). "Using global Nox4 knockout mice and cardiomyocyte‐specific transgenic (TG) mouse models, our previous studies showed that Nox4 is protective against cardiac hypertrophy, contractile dysfunction, and fibrosis in response to pressure overload or myocardial ischaemia." (PMID 33511759, 2021). "In contrast to the epithelial nuclear HDAC1/2 oxidation, NOX4-dependent oxidation promoted nuclear exit of HDAC4 in mouse heart, while mice with NOX4 deficiency in cardiac myocytes were protected against pressure-overload-induced cardiac hypertrophy." (PMID 33802941, 2021). "Previous studies found that NOX4 knockout mice exhibited severe cardiac hypertrophy and contractile dysfunction after pressure overload, whereas NOX4 transgenic mice showed enhanced angiogenesis and increased expression of VEGF and Hif1α as well as less cardiac hypertrophy after pressure overload." (PMID 34513812, 2021). "Additionally, NADPH oxidase 4 (Nox4), a major source of oxidative stress in the failing heart which has been identified, induces cardiac hypertrophy through activating Akt/mTOR and NFκB signaling." (PMID 28479925, 2017). "Upregulation of Nox4 increased mitochondrial superoxide thereby directly mediating oxidative stress, mitochondrial dysfunction, and myocardial cell death during pressure overload-induced cardiac hypertrophy." (PMID 23606925, 2013). "Nox4 mediates cardiac hypertrophy and heart failure in response to pressure overload." (PMID 23606925, 2013). "Nuclear localization of Nox4 has been reported from other cell types such as human vascular endothelial cells and from cardiomyocytes, in which Nox4 causes histone deacetylase 4 (HDAC4) cysteine oxidation, leading to HDAC4 exit from the nucleus and cardiac hypertrophy." (PMID 25645462, 2015). "In a myocardial hypertrophy model established by isoproterenol (ISO) injection, H2S decreased the expression of cleaved caspase-3 and NADPH oxidase 4 (NOX4), inhibited cardiac cell apoptosis, and improved cardiac structure." (PMID 40442106, 2025). "Specifically, the role of ROS regulatory components, such as NADPH oxidases (e.g., NOX2 and NOX4) and their downstream pathways (NRF2/AKT axis) in the progression of cardiac hypertrophy is well documented." (PMID 40779454, 2025). "Cardiac-specific deletion of NOX4 in transgenic mouse models subjected to TAC led to improved LV contractile function and a reduction in cardiac hypertrophy, fibrosis and apoptosis." (PMID 41009041, 2025). "Considering that Nox4, a gene downstream of BRD4, is a major resource for ROS in the heart and can promote cardiac hypertrophy mediated through the Nox4/ROS/ADAM17 pathway, the change in Nox4 protein and mRNA was analysed first." (PMID 37528096, 2023).
cardiac hypertrophy (continued). "In this study, we explored the therapeutic effect of BEL on cardiac hypertrophy and elucidated the mechanism by which BEL confers myocardial protection through the BRD4/Nox4 pathway." (PMID 37528096, 2023). "Mechanistic studies indicate that FGF18/FGFR3 promote FYN activity and expression and negatively regulate NADPH oxidase 4 (NOX4), thereby inhibiting reactive oxygen species (ROS) generation and alleviating pathological cardiac hypertrophy." (PMID 36871047, 2023). "Nox4 is a major enzyme that produces ROS, and oxidative stress involving the Nox4/ROS/ADAM17 signalling pathway was inseparable from the pathogenesis of cardiac hypertrophy." (PMID 37528096, 2023). "Based on the study results, nobiletin can prevent cardiac hypertrophy by reducing NADPH oxidase (NOX) 2 and NOX4 expression." (PMID 36703744, 2022). "Molecular mechanisms linking the HBP to cardiac hypertrophy through GFAT overexpression, high Glc, phenylephrine, NOX4, and STIM1 models." (PMID 36353238, 2022). "In another study, diabetic rats were reported to develop cardiac hypertrophy and further fibrosis analogous to high levels of NOX2 and NOX4." (PMID 36012897, 2022). "We studied therefore the effect of angiotensin II-induced early cardiac hypertrophy on the three major NOX enzymes present in the heart, NOX1, NOX2 (or gp91-phox) and NOX4." (PMID 21151982, 2010). "By contrast, in cardiac-specific, but not systemic, NOX4-knockout (KO) mice, cardiac hypertrophy and dysfunction in response to PO are significantly attenuated due to decreased ROS generation." (PMID 36871047, 2023). "Thus, BEL alleviated cardiac hypertrophy and cardiac dysfunction via the BRD4/Nox4/ROS axes during ISO-induced cardiac hypertrophy." (PMID 37528096, 2023). "Of the NADPH oxidase isoforms expressed in the heart (NOX2 and NOX4), NOX2 may be responsible for β-AR agonist-induced cardiac hypertrophy." (PMID 36986070, 2023). "Also, the production of ROS mediated by NADPH oxidase 4 (NOX4) is required to induce ADAM17 expression and following induction of cardiac hypertrophy." (PMID 36310604, 2022). "In this study, we found that an elevation of Nox4 levels in the endothelium significantly reduces the development of AngII‐induced myocardial fibrosis without affecting the extent of cardiac hypertrophy." (PMID 33511759, 2021). "Upregulation of NOX4 by angiotensin II, which is primary in mitochondria of cardiomyocytes, can also result in inducing nuclear export of histone deacetylase 4 (HDAC4), a crucial precursor of cardiac hypertrophy." (PMID 34660744, 2021). "Moreover, aged (13–14 months) transgenic mice with cardiac-specific overexpression of NOX4 exhibited LV contractile dysfunction with increased myocardial fibrosis, apoptosis, oxidative stress and mitochondrial dysfunction, with no obvious cardiac hypertrophy." (PMID 41009041, 2025). "The cardiomyocyte-specific overexpression of human NOX4, at higher levels that recapitulate upregulation in response to AngII, was sufficient to induce myocardial ROS and fibrosis comparable to AngII treatment, but in the absence of cardiac hypertrophy." (PMID 36139898, 2022). "Ang II, a powerful effector peptide of the RAAS and a hypertrophic agent, can induce cardiac hypertrophy and maladaptive cardiac remodeling by activating different signaling pathways, such as AKT/ERK, TGF-β/SMAD/collagen I/collagen III, NF-κB/NLRP3, NADPH kinases (NOX2 and NOX4)." (PMID 36386139, 2022). "While E2 attenuated cardiac hypertrophy (p = 0.004), it exacerbated proteinuria, decreased GFR (p < 0.05), and failed to reduce aortic NOX4." (PMID 41204447, 2025). "These experiments illustrated that BRD4 acted upstream of Nox4 and that Nox4 did not affect BRD4 protein levels, although both molecules were regulated by BEL, inhibiting genes related to cardiac hypertrophy individually." (PMID 37528096, 2023).
cardiac hypertrophy (continued). "An AII-induced increase in heart weight and heart/body weight were not improved in Nox4 KO mice, indicating that the progression of AII-induced muscle wasting was independent of cardiac hypertrophy." (PMID 29674975, 2018).